CXCL10 (C-X-C motif chemokine ligand 10)
Diseases named in the same sentence as CXCL10 in open-access papers (continued):
Sharing a sentence is not in itself a finding about the gene and the disease.
prostate carcinoma (continued). "CXCL10-upregulated CREB protein levels were also observed in other cancer types, including breast and prostate carcinoma cells, as in transforming growth factor-β (TGF-β)- or interleukin-1 (IL-1)-induced CREB protein upregulation." (PMID 39268223, 2024). "Data generation was done representing multiple genetic variations in TMPRSS2 and CXCL10 mRNA using the cBioPortal database to assess the functional significance of TMPRSS2 and CXCL10 in prostate cancer development." (PMID 36239108, 2022). "We found that the down-regulation of SFMBT2 promotes the infiltration of preadipocytes and TAMs through up-regulation of CXCL8, CCL2, CXCL10, and CCL20 expression in prostate cancer." (PMID 32971847, 2020). "Expression of CXCL8, CCL2, CXCL10, and CCL20 is dependent on NF-κB activation in prostate cancer cells expressing low levels of SFMBT2." (PMID 32971847, 2020). "As with the expression level of CXCL8, CCL2, CXCL10, and CCL20, the number of Pref-1 or CD29 positive cells was increased in prostate cancer tissues with high Gleason scores of ≥8." (PMID 32971847, 2020). "Our analysis indicated the high expression of CXCL8, CCL2, CXCL10, and CCL20 in prostate cancer tissues expressing a low expression level of SFMBT2, which is correlated with high Gleason scores." (PMID 32971847, 2020). "For THP-1 prostate cancer co-cultures, a significant regulation of CXCL1, CXCL10, IL8, and VEGF was observed with plasma treatment." (PMID 32316245, 2020). "Immunohistochemical analysis of human normal and prostate cancer tissue array consistently demonstrated the increased expression of CXCL8, CCL2, CXCL10, and CCL20 in prostate cancer tissues." (PMID 32971847, 2020). "Expression of CXCL8, CCL2, CXCL10, and CCL20 was also elevated in prostate cancer patients having a higher Gleason score (≥8), which had substantially lower SFMBT2 expression." (PMID 32971847, 2020). "We also found that the up-regulation of CXCL8, CCL2, CXCL10, and CCL20 expression is dependent on NF-κB activation in prostate cancer cells expressing a low level of SFMBT2." (PMID 32971847, 2020). "Expression levels of CXCL8, CCL2, CXCL10, and CCL20 in prostate cancer with Gleason scores of ≥8 were higher than those with Gleason scores of ≤7." (PMID 32971847, 2020). "We found that the down-regulation of SFMBT2 promotes the up-regulation of CXCL8, CCL2, CXCL10, and CCL20 expression in prostate cancer cells, resulting in elevated infiltration of preadipocytes and TAMs." (PMID 32971847, 2020). "Further, CP1 induced ICD in both mouse and human prostate cancer cells in vitro, as determined by increased HMGB1, ATP, calreticulin, and CXCL10, and in tumor tissue in vivo, as determined by HMGB1 secretion and increased cell surface calreticulin." (PMID 29686284, 2018). "At intermediate stages of prostate cancer, a considerable number of CXCL10+CD3+ T cells were located inside TLO, and multiple epithelial cells were positive for CXCL10 in tumor areas." (PMID 28567040, 2017). "In prostate cancer cell lines, CXCL4/PF-4 and CXCL10/IP10, both ligands for CXCR3 receptor promote cell motility and invasiveness." (PMID 25298751, 2014). "Also, the expression level of CXCL8, CCL2, CXCL10, and CCL20 was proportionally related to a high Gleason score of ≥8, which seems closely related to prostate cancer invasion and metastasis." (PMID 32971847, 2020). "However, roles of CXCL10 and CCL20 in different cell types are not fully understood in prostate cancer at present." (PMID 32971847, 2020). "We observed the increased expression of CXCL8, CCL2, CXCL10, and CCL20 in prostate cancer tissues induced by intraprostatic injection of LNCaP cells stably transfected with SFMBT2 shRNA compared with prostate tissues injected with LNCaP cells stably transfected with control shRNA." (PMID 32971847, 2020).
prostate carcinoma (continued). "In advanced prostate carcinoma and consistent with the reduction in Tbet+ Th1 cells, we noticed a reduction in CXCL10+CD3+ T cells in TLO but unexplainably observed intense CXCL10 staining in the transformed glandular epithelium." (PMID 28567040, 2017). "In addition, expression of CXCL8, CCL2, CXCL10, and CCL20 was also increased in prostate cancer tissue induced by intraprostatic injection of LNCaP cells stably transfected with SFMBT2 shRNA and in the tissue of prostate cancer patients." (PMID 32971847, 2020). "Since CXCL4/PF4 and CXCL10/IP10 represent the main CXCR3 ligands found during platelet degranulation and thus any hemorrhage and deep in reactive/wounded stromal compartment respectively, we examined functions of these two CXCR3 chemokines on prostate carcinoma cell functioning." (PMID 22236567, 2012). "CXCL10 and CXCL11 as well as CXCR3 are upregulated in lymph node-positive primary prostate cancer in comparison to lymph node-negative prostate cancer." (PMID 39146303, 2024).
chronic hepatitis C (27 papers, 2011 to 2025). "Patients suffering from chronic hepatitis C have significantly elevated CXCL10 levels, and increased CXCL10 levels have been associated with AKI and glomerular pathologies of autoimmune origin." (PMID 32089645, 2020). "Several studies have demonstrated that both MIG/CXCL9 and IP-10/CXCL10 mRNA are elevated in experimental models of liver failure, and circulating levels of both chemokines are implicated in chronic hepatitis C." (PMID 24244295, 2013). "Chronic hepatitis C caused by the hepatitis C virus and intrahepatic interferon-gamma (IFN-γ), which causes increases in CXCL10 production by the sinusoidal endothelium and hepatocytes, subsequently attracting T-cells expressing CXCR3 to the liver." (PMID 38816794, 2024). "CXCL10 was proposed as a biomarker in progressive fibrosis in African-American patients with chronic hepatitis C, and its levels were inversely correlated with the prognosis of interferon therapy." (PMID 37108648, 2023). "In the first study, CXCL10 serum levels were significantly (P < 0.02) higher in patients with chronic hepatitis C (509.8 ± 365.4 pg/mL, mean ± s.d.)than in healthy controls (30.8 ± 20.0 pg/mL, mean ± s.d.)." (PMID 31485460, 2019). "Various organ/tissue-specific diseases caused by increased inflammation, such as chronic hepatitis C virus infection, biliary cirrhosis, psoriatic and osteoarthritis, attract NK cells via the CXCR3/CXCL10 axis; meanwhile, CXCL11-targeted CXCR3 promotes antitumor responses." (PMID 31647037, 2019). "Motivated by the ability to regulate lymphocyte trafficking in vivo, we conducted two prospective clinical trials to test the effects of DPP4 inhibition on CXCL10 processing in healthy donors and in chronic hepatitis C patients, a disease in which DPP4 levels are found to be elevated." (PMID 27137491, 2016). "Moreover, these CXCR3-associated chemokines are associated with intrahepatic inflammation and fibrosis in chronic hepatitis C virus (HCV) infection, and CXCL10 can predict fibrosis progression after liver transplantation for chronic hepatitis C." (PMID 24976843, 2014). "Pretreatment serum levels of interferon-γ-inducible protein-10 (IP-10, CXCL10) and dipeptidyl peptidase-4 (DPP IV) predict treatment response in chronic hepatitis C (CHC)." (PMID 26339796, 2015). "In acute HCV infection, the increases in CXCL9, CXCL10, and CXCL11 with ALT levels follow a similar pattern, while their intrahepatic expression is correlate with liver inflammation and fibrosis in chronic hepatitis C." (PMID 24976843, 2014). "Furthermore, CCL3, CCL4, CCL5, CXCL9, CXCL10 and CXCL11 were found to increase in both liver and peripheral blood during chronic hepatitis C in several studies." (PMID 29284412, 2017).
periodontitis (27 papers, 2013 to 2026). An acute or chronic inflammatory process that affects the tissues that surround and support the teeth. "However, since bone-resorption is a hallmark of progressive periodontitis, our results may indicate that CXCL10 plays a minor role when it comes to bone-resorption since even heat-killed P. gingivalis totally suppressed CXCL10." (PMID 23841502, 2013). "In this group of Portuguese individuals, we found lower levels of IL-23 and IP-10 (CXCL10) in periodontitis patients but higher levels of IL-10." (PMID 39125970, 2024). "Nonetheless, some potential biomarkers were noticed in the serum of patients with periodontitis, such as resistin, C-reactive protein, visfatin, oncostatin M, chemokine CXCL10, and proprotein convertase subtilisin/kexin type 9 (PCSK9)." (PMID 37535199, 2023). "CXCL10 is significantly increased in periodontitis subjects and CXCL10 has been proposed as a marker for periodontal disease." (PMID 35974048, 2022). "In contrast, in other oral inflammatory conditions, such as periodontitis, there appears to be a different chemokine profile with only few biopsy samples demonstrating CXCL10 expression in oral epithelium." (PMID 28253295, 2017). "Interestingly, various studies demonstrated TNF‐α‐induced CXCL10 synergistically contribute to the onset and progression of periodontitis." (PMID 39436204, 2024). "Treatment of both healthy and periodontally diseased gingival fibroblasts with pan-HDACi or HDAC3/6i prior to P. gingivalis infection significantly reduced the induction of a subset of inflammatory mediators (CCL2, CCL5, CXCL10, IL1B, COX2 and MMP3) implicated in periodontitis." (PMID 36291079, 2022). "From an integrated microarray analysis, CXCL10 was identified as a hub gene of periodontitis." (PMID 30847302, 2019). "Immune-inflammatory agents, namely CRP, TNF-α, CXCL10, IL-6, IL-18, sVCAM-1, sICAM-1, IP-10 and MCP-1, have been found in high concentrations in the circulating blood of pregnant individuals diagnosed with preeclampsia who also have periodontitis." (PMID 41394354, 2025). "In patients with periodontitis, the supplementation of the diet with 3g of EPA and 2g of DHA markedly decreased the levels of CXCL1 and CXCL10 measured in the saliva as compared with controls." (PMID 35563819, 2022). "These cells specifically express CXCL10 and CXCL8; CXCL10 is known to be significantly increased in periodontitis secreted in response to IFNγ and binds to its receptor CXCR3, modulating the recruitment of macrophages, T cells, natural killer (NK) cells, and dendritic cells." (PMID 38166489, 2024). "Interestingly, higher levels of all the M1 markers STAT1 (r = .75; p < 0.0001), miR‐155 (r = .8; p < 0.0001), TNF‐α (r = .75; p < 0.0001), and CXCL10 (r = .62; p < 0.001) correlated with PPD in the periodontitis group." (PMID 39436204, 2024). "We did not detect higher LPS or sCD14 levels as markers of bacterial translocation in PLWH with severe periodontitis, nor did we detect an elevation of systemic IL-6, sCD163, CXCL10 as markers of inflammation in PLWH with severe periodontitis." (PMID 36316604, 2023). "Moreover, chemokines such as CXCL8, CXCL10, CXCL12, and CCL5 accumulate in the crevicular fluid of periodontitis patients and their source might be attributed to fibroblasts at least for CXCL2, CXCL3, CXCL8, CXCL9, CXCL10, CXCL12, and CXCL16." (PMID 37762294, 2023).
AIDS (26 papers, 2008 to 2025). A syndrome resulting from the acquired deficiency of cellular immunity caused by the human immunodeficiency virus (HIV). "Since excessive amounts of CXCL10 can be neurotoxic, our findings lend further credence to the role of CXCL10 in progression of AIDS-associated dementia." (PMID 19479051, 2009). "A potential association of pre-infection gene expression of FAM26F, CXCL10 and MX1 with viral replication in macaques immunized with experimental AIDS vaccines from E1 and E2 was also investigated." (PMID 27902344, 2016). "Higher levels of CXCL-10 were detected in jejunal biopsies of AIDS patients with cryptosporidiosis compared with controls." (PMID 22685452, 2012). "It has been reported that CXCL10 is highly upregulated in the IECs of AIDS patients with active cryptosporidiosis." (PMID 22685452, 2012). "In addition, our study also indicated a putative role for novel mediators of HIV-1 immunity, namely ZBP1, LAMP3, CXCL10, LGALS9, and ANKYF1, all of which have been associated with HIV-1/AIDS disease progression." (PMID 35333911, 2022). "In humans, high levels of CXCL10 are produced by IEC in AIDS patients with active cryptosporidiosis; following effective antiparasite and antiretroviral therapy, Cryptosporidium infections resolve, and the levels of CXCL10 decrease to normal." (PMID 24367259, 2013). "Recent studies in the context of HIV mono-infection have shown that higher levels of CXCL10 in the blood were associated with more rapid HIV disease progression and lower CD4+ T cell counts, in addition to being a reliable marker for predicting the progression to AIDS." (PMID 35916523, 2022). "Ex vivo studies of total MMC (containing CD14+ macrophages) isolated from the colon of AIDS patients indicated that these cells secreted increased levels of TNF-α, IL-6, CCL2 and CXCL10 compared to HIV-negative controls." (PMID 26475133, 2015). "Accordingly, the higher expression of inflammatory and pro-inflammatory cytokines, such as CXCL-10 and substance P is present in AIDS patients (compared to AIDS patients without cryptosporidiosis or negative controls)." (PMID 32351207, 2020). "This is in contrast with the predominance of CXCL10 rather than CCL5 in patients with HIV/AIDS during Cryptosporidium infection, and is consistent with the likelihood that the influx of T-cells after C. parvum priming in this model contributed to elevated CCL5." (PMID 27467505, 2016). "In the absence of LPS, unstimulated total MMC from AIDS patients secreted significantly higher levels of macrophage related pro-inflammatory cytokines (TNF-α and IL-6) and chemokines (CCL2, CXCL10) compared to the MMC isolated from healthy controls." (PMID 26475133, 2015). "We detected higher levels of IL-2R, CXCL9, CXCL10, CCL2, and IL-6 (p = 0.001, 0.0003, 0.0002, 0.017, and 0.0005, respectively) in plasma of AIDS patients compared to healthy uninfected controls (data not shown)." (PMID 21125014, 2010).
Insulin resistance (26 papers, 2009 to 2025). Increased resistance towards insulin, that is, diminished effectiveness of insulin in reducing blood glucose levels. "Elevated CXCL10 levels in diabetic patients were found to be associated with an increased risk of inflammation and insulin resistance." (PMID 39065674, 2024). "CXCL10/IP-10 is another potent chemotactic factor with higher expression in obese adipose tissue and circulating levels significantly associated with visceral adipose tissue expansion, insulin resistance and metabolic syndrome." (PMID 37509065, 2023). "FFC-fed CXCL10−/− and WT mice displayed similar weight gain, metabolic profile, insulin resistance, and hepatic steatosis." (PMID 27349927, 2016). "Indeed, FFC-fed CXCL10−/− and WT mice had insulin resistance, similar weight gain and metabolic profiles." (PMID 27349927, 2016). "CXCL10, MCP-1, etc., are very crucial for insulin resistance, activation of JNK, ERK1/2, NF-κB pathways, and recruitment of more inflammatory cells in AT." (PMID 40529363, 2025). "Moreover, HS-BG fiber fermentation produces compounds that restored permeability in disrupted epithelial cells, decreased inflammatory chemokines (CXCL10, MCP-1, and IL-8), and increased anti-inflammatory marker (IL-10), which could improve insulin resistance." (PMID 39064683, 2024).
systemic sclerosis (26 papers, 2011 to 2025). A chronic disorder, possibly autoimmune, marked by excessive production of collagen which results in hardening and thickening of body tissues. "In systemic sclerosis, serum CXCL10 levels strongly correlate with clinical severity of muscle involvement and with CK serum concentration, suggesting a potential mechanistic involvement in muscle damage." (PMID 37891738, 2023). "Human PAH lung tissue had increased IFNAR1 protein expression and circulating levels of the interferon inducible cytokine, IP-10 (or CXCL10) were elevated in patients with systemic sclerosis who had PAH, but not in those without PAH." (PMID 32354189, 2020). "Another study investigated serum CXCL10/11 in very early diagnosis of systemic sclerosis (VEDOSS) and patients with SSc." (PMID 37995465, 2023). "In Systemic Sclerosis (SSc), an autoimmune disorder characterized by important vascular impairments and multiorgan severe failure, CXCL10 and CXCL11 can discriminate those subjects developing SSc from an initial “lighter” condition of very early diagnosis of SSc (VEDOSS)." (PMID 39355618, 2024).